FBP1 (fructose-bisphosphatase 1)
Diseases named in the same sentence as FBP1 in open-access papers (continued):
Sharing a sentence is not in itself a finding about the gene and the disease.
psoriasis (2 papers, 2021 to 2024). An autoimmune condition characterized by red, well-delineated plaques with silvery scales that are usually on the extensor surfaces and scalp. "Fbp1 deficiency in mice facilitates psoriasis-like skin lesions development through glycolysis and acetyl-CoA production." (PMID 38834617, 2024). "Here we find FBP1 is dramatically reduced in human psoriatic lesions and in skin of mice imiquimod psoriasis model, in vivo study demonstrates Fbp1 deficiency facilitates psoriasis-like skin lesions development through glycolysis and acetyl-CoA." (PMID 38834617, 2024). "Fbp1 deficiency also promotes the inflammatory infiltration in animal models of psoriasis in glycolysis and acetyl-CoA-dependent manner." (PMID 38834617, 2024). "Moreover, Fbp1 loss aggravates psoriasis-like skin lesions through glycolysis and acetyl-CoA in the mice imiquimod psoriasis model." (PMID 38834617, 2024). "We further tested whether Fbp1 deficiency affect the development of pathological hyperplasia in psoriasis models." (PMID 38834617, 2024). "Thus, Fbp1 loss aggravates psoriasis-like skin lesions partially through glycolysis and acetyl-CoA production." (PMID 38834617, 2024). "In summary, our study reveals that FBP1 plays critical role in normal skin homeostasis and response to external stimuli, and identifies that FBP1 loss promotes cell state transition and facilitates psoriasis-like skin lesions through metabolite-mediated epigenetic alteration." (PMID 38834617, 2024). "We show here that the gluconeogenic enzyme fructose-1,6-bisphosphatase 1 (FBP1) promotes differentiation while inhibits proliferation of keratinocyte and suppresses psoriasis development." (PMID 38834617, 2024). "The number of infiltrated immune cells was also increased in psoriasis-like skin lesions of Fbp1−/+ mice." (PMID 38834617, 2024). "Collectively, our findings reveal a previously unrecognized role of FBP1 in epidermal homeostasis and provide evidence for FBP1 as a metabolic psoriasis suppressor." (PMID 38834617, 2024). "We further find that the expression of FBP1 is dramatically reduced in human psoriatic lesions and in skin of mouse imiquimod psoriasis model." (PMID 38834617, 2024). "In comparison with healthy controls, FBP1 expression significantly decreased in skin lesions from patients with psoriasis, and to a less extent, decreased in skin lesions from patients with atopic dermatitis." (PMID 38834617, 2024). "We also find FBP1 is dramatically reduced in human psoriatic lesions and Fbp1 deficient mice are more prone to develop IMQ-induced psoriasis-like skin lesions, demonstrating FBP1 participates in psoriasis pathogenesis." (PMID 38834617, 2024). "Other transcripts such as Fbp1 are important in the Nrf2 stress pathway, Stra6 is involved in vitamin A transport in a murine psoriasis model, and 2 transmembrane proteases (Tmprss11e/f) are involved in skin barrier function." (PMID 34823472, 2021). "Our results uncover a previously unrecognized role of FBP1 in epidermal homeostasis and suggest that restoring FBP1 in psoriatic lesions might be a promising approach for treating psoriasis." (PMID 38834617, 2024). "Thus, targeting glycolysis or acetyl-CoA production may represent potential treatment for psoriasis patients with reduced FBP1 expression in skin lesions." (PMID 38834617, 2024). "Importantly, elucidating the reason why FBP1 is downregulated in psoriasis may help to restore FBP1 level and alleviate psoriasis in the future." (PMID 38834617, 2024). "We next examined whether 2-DG or 2-HC alleviated psoriasis-like phenotype in Fbp1−/+ mice." (PMID 38834617, 2024). "However, to our knowledge, the role of FBP1 in epidermal homeostasis and psoriasis has not been studied." (PMID 38834617, 2024).
Arthritis (1 paper, 2025). Inflammation of a joint. "A recent study has provided a new insight into the molecular mechanism underlying the anti-inflammatory effect of FBP1, a high-energy intermediate of glycolysis, in effectively attenuating experimental arthritis." (PMID 40807147, 2025).
biliary tract cancer (1 paper, 2024). "In biliary tract cancer cell lines, Tazemetostat has been demonstrated to effectively reduce levels of H3K27me3 and upregulate the gene expression of fructose-bisphosphatase 1 (FBP1)." (PMID 39703687, 2024).
breast tumor (1 paper, 2020). "We analyzed PIM2 and FBP1 Ser144 phosphorylation expression levels by western blot in breast tumors (T) and their adjacent normal tissues (N)." (PMID 32754266, 2020). "As a result, phosphorylation of FBP1 on Ser144 promoted breast tumor growth in vitro and in vivo." (PMID 32754266, 2020). "Furthermore, FBP1 Ser144 phosphorylation stimulated breast tumor growth in vivo, as detected in athymic nude mice." (PMID 32754266, 2020). "FBP1 phosphorylation by PIM2 promoted breast tumor growth and p65-induced PD-L1 expression, highlighting the role of PIM2-dependent FBP1 phosphorylation in breast tumor progression." (PMID 32754266, 2020).
cardiac sarcoidosis (1 paper, 2023). Sarcoidosis affecting the tissues of the heart. "We also compared gene expression in FBP1-positive TREM2 macrophages in the skin and heart using single-nucleus RNA-Seq data for cardiac sarcoidosis in public databases." (PMID 38038136, 2023).
cerebral oedema (1 paper, 2022). "Whilst the preservation of glycolysis contributes to reduced clinical severity, undiagnosed FBP1 deficiency is potentially fatal, particular if fructose, sucrose or glycerol containing intravenous solutions are used to manage acute crises or ensuing complications such as cerebral oedema." (PMID 35281660, 2022).
cervical cancer (1 paper, 2020). A primary or metastatic malignant neoplasm involving the cervix. "Experiments validated that the overexpression of FBP1 significantly inhibits tumor cell growth and restores the chemosensitivity of cervical cancer cells by suppressing the glycolytic process." (PMID 32038983, 2020). "Compared with normal tissues, FBP1 mRNA levels were significantly decreased in cervical cancer cells, and the downregulation of FBP1 expression was closely related to tumor recurrence and tumor stage in cervical cancer patients." (PMID 32038983, 2020).
chronic kidney disease (1 paper, 2026). Impairment of the renal function secondary to chronic kidney damage persisting for three or more months. "A machine learning-selected biomarker panel (PDK4, RHCG, FBP1) demonstrated strong diagnostic value (area under the curve, AUC > 0.9), with consistent downregulation across multiple chronic kidney diseases." (PMID 41481634, 2026).
cognitive decline (1 paper, 2022). "Thus, the omics data reveal that the reduced FBP1 and ALDOB and increased UQCRC2 can contribute to cognitive decline in T2DM patients through the mechanisms involving deregulated glucose metabolism and acidosis." (PMID 36506101, 2022).
encephalitis (1 paper, 2025). An acute inflammatory process affecting the brain parenchyma. "The most prominent fold increases in encephalitis compared to meningitis patients were SAM (2.5-fold), FBP1 (3.2-fold), 1-Methylnicotinamide (MNA) (2.3-fold) and PEP (2.5-fold)." (PMID 40517242, 2025). "CSF S-Adenosylmethionine (SAM), Fructose 1,6-bisphosphate (FBP1) and Phosphoenolpyruvic acid (PEP) levels were 2.4-fold (range ≥ 2.3-≥3.2) higher in encephalitis patients compared to the meningitis group." (PMID 40517242, 2025).
endometrial cancer (1 paper, 2019). Primary or metastatic malignant neoplasm involving the endometrium (mucous membrane that lines the endometrial cavity). "Among these survival-related genes, five genes (EPHB2, FBP1, NLRC3, PPP2R3A, and TRIM46) were included in a previously reported 9-gene signature for predicting endometrial cancer patient survival." (PMID 30847026, 2019).
esophageal adenocarcinoma (1 paper, 2022). A malignant tumor with glandular differentiation arising predominantly from Barrett mucosa in the lower third of the esophagus. "We describe, for the first time, the prognostic and possibly therapeutic relevance of FBP1 in a large cohort of patients with esophageal adenocarcinoma." (PMID 35477823, 2022).
Fanconi anemia (1 paper, 2023). Fanconi anemia (FA) is a hereditary DNA repair disorder characterized by progressive pancytopenia with bone marrow failure, variable congenital malformations and predisposition to develop hematological or solid tumors. "miR-24-1 upregulated the expression of its adjacent genes fructose-1,6-bisphosphatase 1 (FBP1) and Fanconi anemia, complementation group C (FANCC) in HEK293T cells." (PMID 37176056, 2023).
fructose intolerance (1 paper, 2025). "An example for this scenario in our cohort are four patients presenting with a GSD phenotype but two of them were diagnosed as hereditary fructose intolerance (ALDOB gene) and the other two had fructose 1,6 bisphosphatase deficiency (FBP1 gene)." (PMID 41165782, 2025).
fungal meningitis (1 paper, 2024). Meningitis caused by fungal agents which may occur as opportunistic infections or arise in immunocompetent hosts. "For instance, Fbp1, as an integral component of the SCF E3 ligase complex, is indispensable for the full virulence of Cryptococcus neoformans which causes fungal meningitis in humans." (PMID 39594040, 2024).
Granuloma (1 paper, 2023). A compact, organized collection of mature mononuclear phagocytes, which may be but is not necessarily accompanied by accessory features such as necrosis. "Since sarcoidosis results in granulomas in various organs throughout the body, we examined FBP1 expression in granulomas of tissues other than the skin by immunostaining." (PMID 38038136, 2023). "We added 6-aminonicotinamide (6AN), a G6PD inhibitor, and 2,5-dichloro-N-(5-chloro-2-benzoxazolyl)-benzenesulfonamide, an FBP1 inhibitor (FBPi) in this in vitro granuloma model." (PMID 38038136, 2023). "FBP1-positive TREM2 macrophages constitute granulomas in sarcoidosis." (PMID 38038136, 2023). "FBP1 expression was also detected in granulomas of the lung, heart, and lymph nodes." (PMID 38038136, 2023). "Immunohistochemistry of sarcoidosis skin samples showed positivity for TREM2 and FBP1, which is consistent with the accumulation of CD68-positive cells in granuloma areas." (PMID 38038136, 2023). "In granulomatous skin disease, FBP1 expression was detected in CD68-positive granuloma regions, while CD163 was observed surrounding FBP1-positive regions." (PMID 38038136, 2023).
hepatitis C (1 paper, 2016). "Therefore, the expression of DUOX1, GLS2and FBP1 may change in the patients with hepatitis C and NASH." (PMID 27079415, 2016).
Huntington disease (1 paper, 2022). Huntington disease (HD) is a rare neurodegenerative disorder of the central nervous system characterized by unwanted choreatic movements, behavioral and psychiatric disturbances and dementia. "Furthermore, Gene Set Enrichment Analysis supports that not only glycolysis and gluconeogenesis but also the kinetochore metaphase signaling pathway, Wnt//β-catenin signaling, sperm motility, and Huntington's disease signaling may play a role in regulating ALDOA and FBP1." (PMID 35404841, 2022).
hyperalaninemia (1 paper, 2022). "As a rate-limiting enzyme, FBP1 catalyzes the reaction of fructose 1,6-bisphosphate to fructose 6-phosphate, while the deficiency of FBP1 increases the levels of uric acid and hyperalaninemia with the consequence of metabolic acidosis or ketosis." (PMID 36506101, 2022).
infertile (1 paper, 2017). "The expression of some proteins, including FBP1, were altered and their functions may be damaged in infertile men with unilateral varicocele." (PMID 29162033, 2017).
inflammatory skin disease (1 paper, 2023). Inflammatory skin disorders covers a broad category that includes many conditions ranging in severity, from mild itching to grave medical health complications These disorders are common in people of all ages and races. "In contrast, no FBP1-positive cells were observed in nongranulomatous inflammatory skin diseases." (PMID 38038136, 2023).
lentivirus infection (1 paper, 2024). Virus diseases caused by the Lentivirus genus. "The findings revealed a significant increase in FBP1 expression at 48-h post-lentivirus infection compared to 24 h post-infection." (PMID 38349431, 2024).
lung squamous cell carcinoma (1 paper, 2022). "Additionally, high FBP1 correlates with lung squamous cell carcinoma, and low FBP1 correlates with uterine corpus endometrial cancer (p=0.00052)." (PMID 35404841, 2022).
lymphoma (1 paper, 2023). A malignant (clonal) proliferation of B- lymphocytes or T- lymphocytes which involves the lymph nodes, bone marrow and/or extranodal sites. "We further hypothesize that lymphoma susceptibility might be aggravated by the additional mutations in FBP1 and ACAD9, affecting energy metabolism and – potentially – killing activity in NK cells and CTLs." (PMID 37388727, 2023).
minimal change disease (1 paper, 2025). "Notably, three proteins—ACAT1, MME, and FBP1—with the highest expression levels observed in minimal change disease (MCD) showed kidney tissue specificity." (PMID 40283082, 2025).
nephropathies (1 paper, 2026). "Further analysis revealed that while RHCG exhibited distinct expression patterns in DKD compared to other nephropathies, FBP1 and PDK4 showed comparable expression levels across disease types." (PMID 41481634, 2026).
nephrotic syndrome (1 paper, 2023). A collection of symptoms that include severe edema, proteinuria, and hypoalbuminemia; it is indicative of renal dysfunction. "Group 1 was characterized by major risk genes for developing LOAD (APOC1 and APOC1P1) and immune-related genes (RELB and CBLC), whereas group 2 was characterized by genes associated with kidney disorders, such as nephrotic syndrome (AXDND1, FBP1, and MIR2278)." (PMID 37386009, 2023).
nonimmune hydrops fetalis (1 paper, 2025). "While the prenatal phenotype of fructose‐1,6‐bisphosphatase deficiency is not well characterized, we hypothesize that the FBP1 gene variant detected in Case 82 could explain the increased nuchal translucency, as inborn errors of metabolism are known to cause nonimmune hydrops fetalis." (PMID 41317105, 2025).
Obesity (1 paper, 2021). Accumulation of substantial excess body fat. "FBP1 is a gluconeogenesis enzyme that is promoted by obesity and high fat intake." (PMID 33807173, 2021).
psychosis (1 paper, 2016). "Of these validated MAP biomarkers, four were previously reportedto predict psychosis in an independent human blood transcriptomeinvestigation (FBP1, ZNF821, TBC1D2 andSIN3A), one of which was previously labelled a genetic variantfor SCZ risk (FBP1)." (PMID 27163203, 2016).
sarcoidosis (1 paper, 2023). Sarcoidosis is a multisystemic disorder of unknown cause characterized by the formation of immune granulomas in involved organs. "The proportions of APCs expressing ACE (a previously established diagnostic marker for sarcoidosis) and FBP1 (a newly discovered marker in this study) in skin lesions were analyzed in granulomatous skin diseases other than sarcoidosis." (PMID 38038136, 2023). "Here, we demonstrated that FBP1-positive TREM2 macrophages are increased in human sarcoidosis lesions and that serum FBP1 levels are increased in sarcoidosis patients." (PMID 38038136, 2023). "Elevated serum FBP1 levels were also observed in sarcoidosis patients." (PMID 38038136, 2023). "Serum concentrations of FBP1 were significantly elevated in patients with sarcoidosis." (PMID 38038136, 2023). "Thus, FBP1-positive TREM2 macrophages share a typical phenotype among organs involved in sarcoidosis." (PMID 38038136, 2023). "Therefore, FBP1 inhibition may serve as a therapeutic agent for sarcoidosis with fewer side effects." (PMID 38038136, 2023). "Expression of the PPP enzymes, such as fructose-1,6-bisphosphatase 1 (FBP1), was elevated in both systemic granuloma lesions and serum of sarcoidosis patients." (PMID 38038136, 2023). "Consistently, FBP1-positive TREM2 macrophages were also found in the granulomas in the lung, heart, and lymph nodes of sarcoidosis patients." (PMID 38038136, 2023).
schizophrenia (1 paper, 2008). A major psychotic disorder characterized by abnormalities in the perception or expression of reality. "The C alleles of both rs4129219 and rs1040566 in each of the FBP1 and the PCK1 gene showed nominal association with elevated risk for schizophrenia." (PMID 18460190, 2008). "As we cannot draw firm conclusions with the current data further investigations with testing of more loci are required to clarify whether ENO2, FBP1, MAPK14 and PCK1 variants provide genetic support for the view that alterations in glucose metabolism are intrinsic to schizophrenia etiology." (PMID 18460190, 2008).
squamous cell carcinoma (1 paper, 2024). A carcinoma arising from squamous epithelial cells. "Additionally, we also found FBP1 and CDC6 levels were dramatically reduced in skin lesions from patients with squamous cell carcinoma (SCC) using dataset GSE191334, implicating FBP1 might also participate in SCC development." (PMID 38834617, 2024).
tuberous sclerosis (1 paper, 2024). Hereditary disease characterized by seizures, intellectual disability, developmental delay, and skin and ocular lesions. "Alterations in succinate dehydrogenase (SDH), tuberous sclerosis (TSC) and fructose-1,6-bisphosphatase 1 (FBP1) represent additional lesions that drive metabolic reprogramming in kidney cancer." (PMID 39149323, 2024).
urothelial carcinoma (1 paper, 2008). A malignant neoplasm derived from the transitional epithelium of the urinary tract (urinary bladder, ureter, urethra, or renal pelvis). "FBP1 immunohistochemistry was evaluable in 112 urothelial carcinomas." (PMID 19087307, 2008).